IL6 (interleukin 6)
Diseases named in the same sentence as IL6 in open-access papers (continued):
Sharing a sentence is not in itself a finding about the gene and the disease.
pancreatic cancer (continued). "Interestingly, IL-6 pathway inhibitors are currently tested in combination with chemotherapy in patients with BCA (NCT03135171), pancreatic cancer (NCT04258150, NCT02767557), or liver cancer (NCT04338685), who displayed potent anti-cancer activity with a low incidence of IL-6 drug toxicity." (PMID 37480115, 2023). "Considering that IL-6 and sIL-6R levels are often elevated in various pathological conditions including pancreatic cancer, endogenous sgp130 may not be sufficient to keep the overactive IL-6 trans-signaling in check." (PMID 36551971, 2022). "The IL-6/STAT3 signaling pathway has been proposed as a major linking mechanism between the inflammatory tumor microenvironment and pancreatic cancer, which may promote the initiation and progression of tumors by regulating oncogenes and epigenetic modifications of tumor suppressor genes." (PMID 36105933, 2022). "There are also some clinical reports of resectable pancreatic cancer patients, which noted low levels of the described pro-inflammatory cytokines (IL-6, IL-1β, IFN-γ, and TNF-α), with their concentrations not correlated with CC, even if more sensitive methods were used for the analyses." (PMID 33557173, 2021). "Regarding the effects of OSM in mediating stemness and pluripotency, OSM was shown to induce a mesenchymal CD44 high/CD24 low phenotype in breast and pancreatic cancer cells, and this action was unique to OSM and not observed following IL-6 exposure in pancreatic cancer cells." (PMID 34361105, 2021). "It is worth mentioning that the IL-6 produced by non-neoplastic components within pancreatic tumors could activate proinflammatory STAT3 signaling in hepatocytes." (PMID 32724299, 2020). "These cytokines, such as interleukin-1β (IL-1β), IL-6, IL-8, IL-10, tumor necrosis factor-α (TNF-α), and transforming growth factor-β (TGF-β) are potential prognostic biomarkers as well as targets in the pathogenesis of pancreatic cancer and in peripheral nerve injury." (PMID 32174830, 2020). "Moreover, IL-6 signaling (IL-6, LIF, or OSM) has been described to be important for CSC induction and maintenance in breast, ovarian, endometrial, and pancreatic cancers." (PMID 31554173, 2019). "The direct or indirect effects of IL-6, IL-8, IL-10, TGF-β, C-C motif chemokine ligand 2 (CCL2), C-X-C motif chemokine ligand 9 (CXCL9), and CXCL10, but not limited to those, on tumor immunity in patients with oral, breast, and pancreatic cancer have been investigated." (PMID 31281359, 2019). "Furthermore, we show that LIF, but not IL-6, inhibits the activity of the Hippo-signaling pathway in pancreatic cancer cells." (PMID 31296870, 2019). "Thus, IL-6 appears to be a better prognostic biomarker than CA 19.9 in non-operable pancreatic cancer patients, but CA 19.9 is a better prognostic biomarker for pancreatic cancer patients who undergo surgery." (PMID 30038723, 2018). "Increased IL-6 along with decreased IFN-γ and cell-mediated cytotoxicity by the NK cells, within NK-adipose tissue of KC/HFCD mice, may provide safe microenvironment for the expansion of pancreatic tumors." (PMID 29977235, 2018). "In addition, it has been proven that IL-6 is involved in the activation of macrophage phenotype switch, which takes place in the TME, followed by stimulated expression of EMT markers such as N-cadherin and vimentin in pancreatic cancer cells." (PMID 29254283, 2017). "IL-6 and IL-10 were significantly increased in both the HCC and GBC groups, whereas IL-2, IL-6, IL-10, and TNF-α were significantly increased in the cholangiocellular carcinoma group, and IL-2, IL-6, IL-8, and TNF-α were significantly increased in the pancreatic cancer group." (PMID 29410961, 2017). "Moreover, the Milliplex assay showed that FH535 significantly decreased VEGF, IL-6, IL-8, and TNF-α levels in culture medium, indicating that the WNT/β-catenin pathway–targeting strategy represses angiogenesis in pancreatic cancer through a mechanism involving multiple genes." (PMID 27323403, 2016).
pancreatic cancer (continued). "Inflammatory cytokine IL-6 was significantly increased after the first cycle of vaccination in the PPV alone group, but not in the PPV plus JTT group, suggesting that combined usage of JTT inhibited plasma IL-6 elevation in pancreatic cancer patients undergoing PPV." (PMID 23840274, 2013). "Odds ratios (ORs) for prediction of pancreatic cancer were significant for all biomarkers, with CA 19.9 having the highest AUC (CA 19.9: OR = 2.28, 95% CI 1.97 to 2.68, p<0.0001, AUC = 0.94; YKL-40: OR = 4.50, 3.99 to 5.08, p<0.0001, AUC = 0.87; IL-6: OR = 3.68, 3.08 to 4.44, p<0.0001, AUC = 0.87)." (PMID 23840582, 2013). "Therefore, our findings suggested that inhibition of IL-6 production by QYHJ might result in reduced EMT and invasion in pancreatic cancer." (PMID 23922983, 2013). "Indeed, therapeutic approaches targeting IL-6 signaling in neoplasia have been successful in preclinical settings, but anti-IL-6 monotherapy in clinical trials for colorectal, ovarian and pancreatic cancers showed no beneficial outcome, possibly because of signaling alterations." (PMID 36639824, 2023). "Aberrant IL-6 and IL-18 levels both create a tumor microenvironment that is favorable for the tumor cells by promoting survival and establishing an immunosuppressive environment, suggesting that NLRX1 may protect against pancreatic tumors through regulating inflammation and inflammatory cytokines." (PMID 37342194, 2023). "Furthermore, hepatocytes induce release of serum amyloid A via Interleukin 6 (IL-6)-mediated Signal transducer and activator of transcription 3 (STAT3) activation to promote the establishment of a hepatic PMN which facilitates liver metastasis of pancreatic cancer in a xenograft mouse model." (PMID 37941082, 2023). "In addition, hypoxia has been found to induce expression of vascular endothelial growth factor (VEGF), IL-6, and CSC signature genes such as Nanog and Oct4 with increased cell migration/invasion, concomitant with the upregulation of miR-210 expression in human pancreatic cancer cells." (PMID 34299605, 2021). "However, few serum markers of chronic inflammation have been investigated in relation to CP and pancreatic cancer diagnosis (mainly CRP and cytokines such as Interleukin-6 (IL-6) and Tumour Necrosis Factors (TNF-α)), partially because CP may elevate pancreatic enzymes instead." (PMID 31464604, 2019). "In this study, we observed that pancreatic cancer cells could induce macrophages to exhibit a tumor-promoting phenotype, and then the tumor-promoting macrophages induced CD59 expression in cancer cells by IL-6 secretion and by inducing IL-6R expression in cancer cells." (PMID 31685825, 2019). "Despite numerous positive pre-clinical data proving the beneficial outcome of IL-6 targeting in PDAC, the complete lack of IL-6 in the TME of PDAC had surprisingly no significant impact on the development of pancreatic cancer in mouse models." (PMID 37174079, 2023). "A second CAF subpopulation located more distant to pancreatic cancer cells did not express elevated α-SMA levels and was characterized by the production of pro-inflammatory cytokines, such as IL-6." (PMID 36544698, 2022). "Overexpression of ZIP4 may cause activated IL-6/STAT3 pathway and also led to increased VEGF and MMP expression, however, the detailed mechanism of how ZIP4 overexpression causes the activation of the downstream signalling pathways to promote pancreatic cancer growth is not clear." (PMID 23857777, 2013). "This association of zinc transporters with STAT3 is not unprecedented as ZIP14 is regulated by IL-6 (interleukin 6) and STAT3 signalling and ZIP4 activates STAT3 transcription in pancreatic cancer." (PMID 23919497, 2013). "Although IL-6 and Socs3 mRNA expression did not significantly change in the gastrocnemius muscle of RM9-bearing mice, IL6ra was increased similar to what others have observed in a murine pancreatic cancer cachexia model." (PMID 35785158, 2022).
pancreatic cancer (continued). "Our previous study has shown that bazedoxifene is capable of blocking the IL6/GP130/STAT3 signaling pathway by inhibiting IL6‐induced homodimerization of GP130, leading to a potential antitumor effect, which has been demonstrated in triple‐negative breast cancer and pancreatic cancer." (PMID 39152779, 2024).
gastric cancer (441 papers, 2004 to 2026). A primary or metastatic malignant neoplasm involving the stomach. "Together, these results demonstrate that antagonizing miR-BART20-3p upregulates PPARα and concomitantly downregulates IL-6, reinforcing the functional miR-BART20-3p–PPARα–IL-6 axis in EBV-associated gastric cancer." (PMID 40732023, 2025). "According to the results of a study in which MDSCs and MKN45 cells were cocultured, MDSCs stimulate the growth and colony‐forming potential of gastric cancer cells, which causes MDSCs to release IL‐6." (PMID 41179371, 2025). "IL-6 emerges as a particularly important cytokine in this context, as it has been consistently associated with poor prognosis in patients with gastric cancer." (PMID 40940839, 2025). "This inflammatory cytokine profile mirrors that observed in human chronic gastritis and gastric cancer, where elevated IL-17, IL-6, and TNF-α levels are associated with increased cancer risk and poor prognosis." (PMID 40673273, 2025). "This inflammatory signature mirrors the tumor microenvironment of human KRAS-mutated gastric cancers, which often exhibit elevated interleukin-6 signaling and enhanced C-X-C motif chemokine ligand 1-mediated neutrophil recruitment." (PMID 40673273, 2025). "We aimed to explore the role of IL-6 in H. pylori-associated gastric cancer and show that macrophages and epithelial cells demonstrate both autocrine and paracrine IL-6 induction, which is enhanced by H. pylori." (PMID 38422751, 2024). "Xiongyan Wu and colleagues concluded that cancer-associated fibroblasts (CAFs) isolated from gastric cancer can activate the JAK2/STAT3 pathway in gastric cancer cells by secreting IL-6." (PMID 39309860, 2024). "A comprehensive study revealed that CAF-derived IL-6 causes resistance to 5-FU in vitro and in vivo models of gastric cancer." (PMID 38562556, 2024). "Our work previously demonstrated a strong causal link of gp130 proinflammatory cytokines IL-6, and more so, IL-11 in the development of gastric cancer." (PMID 37957015, 2024). "Retrospective clinical data revealed that high levels of IL-6, p-Stat3, and PD-L1 are associated with a decrease in the integrity of the gastric cancer environment, which is correlated with suboptimal patient survival rates." (PMID 39309860, 2024). "It was found that PF acted on gastric cancer AGS cells and inhibited the migration and invasion-promoting ability of gastric cancer-associated fibroblasts (GCAFs) by targeting microRNA-149 and IL-6." (PMID 38611704, 2024). "The 1.97-pg/ml serum level of IL-6 with 81.8% sensitivity and 66.7% specificity is found to be the optimal diagnostic cutoff for gastric cancer." (PMID 37746258, 2023). "Just to cite an example: one study found that IL-6 efficiently protects gastric cancer cells from apoptosis caused by hydrogen peroxide (H2O2) by increasing the production of Mcl-1 (an anti-apoptotic protein)." (PMID 37759738, 2023). "It has been found that gastric cancer-associated MSCs, by secreting IL-6 and IL-8 cytokines, as well as the JAK2/STAT3 signaling pathway, have caused the polarization of macrophages towards M2 macrophages, which promotes tumor growth." (PMID 38022534, 2023). "Cancer-associated fibroblasts (CAFs) induce IL-6 to activate the Jak1-STAT3 pathway in gastric cancer cells by paracrine signaling." (PMID 37176567, 2023). "Chronic inflammation measured based on TNF-a, CRP, and IL-6, among others, is highly correlated with an increased risk of gastric cancer; those measurements can be practical in predicting gastric cancer development at very early stages." (PMID 38068839, 2023).
gastric cancer (continued). "According to literature, an increase of the LINC00460 leads to a reduction of mir-149 (in the cell line SUNE-19), and, in turn, the decrease of mir-149 leads to an increase of IL-6 (in cancer-associated fibroblasts in the stroma in gastric cancer)." (PMID 35915466, 2022). "The chemical precursor of MaSS is kaempferol, which is capable of reducing IL-6 levels in people with peptic ulcer disease, which is a risk factor for stomach cancer." (PMID 36365404, 2022). "The aim of the study was to assess the association of perioperative serum interleukin-6 (IL6) and tumor necrosis factor-α (TNFα) levels with the 5-year overall survival in locally advanced gastric cancer." (PMID 35859928, 2022). "Perioperative high serum IL6 and TNFα levels are negatively associated with 5-year survival outcomes in patients with locally advanced gastric cancer, indicating the potential survival benefits from perioperative anti-inflammatory treatment." (PMID 35859928, 2022). "The development of gastric cancer has been known to be closely associated with chronic inflammation accompanied by significantly elevated IL-6 concentration." (PMID 31148950, 2019). "Although the number of studies of patients with gastric cancer was small, all studies found a significant association between high serum IL-6 and short OS, suggesting a prognostic value in gastric cancer." (PMID 30038723, 2018). "Recent studies have shown that aberrant expression of IL-6 is tightly linked to tumor generation and poor disease outcome in many cancer types, including gastric cancer." (PMID 28186964, 2017). "Various studies have linked IL-6 to gastric cancer, though few studies have investigated clinical cutoffs of IL-6 for this condition." (PMID 28487810, 2017). "Aberrant production and signaling of IL-6 is tightly linked to tumor generation and poor disease outcome in many cancer types, including gastric cancer." (PMID 28186964, 2017). "Expression of transcripts encoding multiple pro-inflammatory cytokines previously implicated in gastric cancer was also elevated, including IL-6, IL-11, IL-1β, and TNFα." (PMID 26859571, 2016). "We found that systemic levels of only selected ILs and/or IL ratios (IL-6, IL-8, IL-6/IL-8 and IL-6/IL-10) showed potential as diagnostic markers for the detection/discrimination of gastric cancer (with a sensitivity and specificity of approximately 54–72%)." (PMID 26486258, 2015). "The prognostic role of the functional IL-6 (promoter) rs1800795 and the IL-6R (receptor) rs8192284 single nucleotide polymorphisms (SNP) was studied in patients with advanced gastric cancer treated with palliative chemotherapy." (PMID 24886605, 2014). "Like IL-8, the expression of IL-6 is higher in gastric cancer than in normal tissues, and is implicated in tumour metastasis." (PMID 25350954, 2014). "In the present study, we found that IL-6 expression was significantly associated with NF-κB, and both were found overexpressed in human gastric cancer; a weak expression was found in adjacent normal mucosa." (PMID 23117246, 2013). "For example, a composite score combining TNF-α, CA19-9, and perhaps IL-6 (another cytokine tied to gastric cancer prognosis) might better identify high-risk patients than any single marker." (PMID 40299527, 2025). "Meanwhile, gastric cancer tissue‐derived mesenchymal stem cells (GC‐MSCs) was proved to possess the ability to transfer into cancer‐associated fibroblasts (CAFs) under the stimulation of IL‐6 and TNF‐α which promote tumor progression." (PMID 38349050, 2024). "In this scenario, the role of the IL-6/STAT3 pathway may represent a target for innovative gastric cancer therapeutic strategies often associated with clinically aggressive features and resistance to conventional therapy." (PMID 36979673, 2023). "ROC curve of the diagnostic power of serum SAA and IL-6 level for gastric cancer." (PMID 36316846, 2022).
gastric cancer (continued). "In addition to the textural features of perigastric AT, the maximum SUV of gastric cancer showed a significant positive association with macrophage infiltration and a borderline significant association with IL-6 expression in perigastric AT." (PMID 36233285, 2022). "Furthermore, IL-6 derived from tumor-associated fibroblasts infiltrating into gastric cancer microenvironment can promote epithelial-mesenchymal transition (EMT)." (PMID 33144870, 2020). "An increase in the ratio of IL6/IL10 has been associated with gastric cancer prognosis." (PMID 32256476, 2020). "Since IL-6 causes an increase of migration and invasiveness in gastric cancer cells, we investigated the effect of LPE treatment on rIL-6-induced migration and invasive ability by wound healing and matrigel invasion assays, respectively, in MKN-28 and AGS cells." (PMID 31817563, 2019). "However, despite considerable precedent, a 2005 study found the optimal diagnostic cutoff of IL-6 for gastric cancer to be 1.97 pg/mL (sensitivity 81.8%; specificity: 66.7%)." (PMID 28487810, 2017). "Besides IL-1and IL-1R1, many other cytokines and associated receptors, for example IL-6 and TNFα, are involved in the progression of gastric cancer and can activate NF-κB signaling." (PMID 26870992, 2016). "Furthermore, IL-6 has been shown to be produced primarily by stromal fibroblasts in a gastric cancer mouse model; however, the deficient mouse model exhibits reduced tumorigenesis when exposed to the carcinogen N-methyl-N-nitrosourea." (PMID 24901008, 2014). "Notably, we found that the common G allele of the IL-6 promoter variant (rs1800795) showed association with poor survival of patients with advanced gastric cancer treated with palliative chemotherapy." (PMID 24886605, 2014). "However, high IL-6 and CRP levels were related to advanced stage, including distant metastasis, in this study, and elevated IL-6 levels were associated with poor outcomes in cases of gastric cancer." (PMID 19457231, 2009). "In contrast, in a Korean study of gastric carcinoma patients who underwent gastrectomy, elevated serum IL-6 was significantly associated poorer disease status and OS in univariate but not multivariate analysis although it is unclear whether these patients received perioperative treatment." (PMID 41249451, 2026). "With regard to gastric cancer, dopamine is also a major factor involved in inflammation regulation, influencing chronic inflammation and inducing oxidative stress, DNA mutations, and anti-inflammatory effects while reducing the production of tumor necrosis factor α and interleukin 6 (IL-6)." (PMID 39767693, 2024). "Notably, gastric cancer was associated with elevated IL-6 levels in biological fluids." (PMID 31010015, 2019). "However, the consensus between the two studies regarding the role of IL-6 in predicting gastric cancer suggests that the correct cytokine for diagnostic use has been identified and that it will just be a matter of time to establish a narrower diagnostic cutoff range with improved sensitivity." (PMID 28487810, 2017). "IL11: Although belonging to the IL6 cytokine family and known for its pro-tumorigenic roles in lung and gastric cancers our results represent the first report of its dysregulation in cSCC." (PMID 41438693, 2026). "We then validated that miR-BART20-3p binds the PPARα 3′-UTR to suppress its expression and demonstrated that miR-BART20-3p promotes proliferation, migration, and IL-6 upregulation via PPARα inhibition in gastric cancer cells." (PMID 40732023, 2025). "Targeting and blocking the IL-6/STAT3 pathway therefore represents an effective therapeutic strategy for gastric cancer." (PMID 40051564, 2025). "Studies on MCL have shown that it suppresses gastric cancer growth by blocking the IL-6/STAT3 pathway." (PMID 40051564, 2025).